S100A9 (S100 calcium binding protein A9)
Diseases named in the same sentence as S100A9 in open-access papers (continued):
Sharing a sentence is not in itself a finding about the gene and the disease.
cardiovascular disease (23 papers, 2013 to 2025). "S100A9 levels in plasma are also used to predict cardiovascular disease risk and to detect acute cardiovascular events, such as atherosclerotic plaque rupture and thrombosis." (PMID 36531717, 2022). "We were also able to demonstrate an association of CEBPD, and S100A8 and S100A9 expression in the context of human cardiovascular disease." (PMID 35543413, 2022). "Together with S100A9 it forms a heterodimer (Calprotectin) and is considered a danger-associated molecular pattern, especially in cardiovascular diseases." (PMID 34072201, 2021). "S100A9 was found to be implicated in various cardiovascular disorders." (PMID 40384874, 2025). "S100A9 can serve as a biomarker for diagnosis, prediction, and evaluation of cardiovascular diseases, and it is also considered a potential therapeutic target." (PMID 38504474, 2024). "S100A9, a pivotal inflammatory modulator, has been reported to participate in the development and progression of diverse cardiovascular disorders." (PMID 38504474, 2024). "Among the S100 family of binding proteins S100A8, S100A9, and S100A12 have been identified as DAMPs and linked with cardiovascular disease (CVD)." (PMID 38275751, 2023). "Drugs targeting the S100A8/S100A9 complex leading to modulation of inflammatory response have been proposed in the treatment of cardiovascular disease." (PMID 26222498, 2015). "The involvement of S100A8 and S100A9, DAMPs belonging to the S100 calgranulin family, in the pathogenesis of cardiovascular disease is attracting an increasing amount of interest." (PMID 24453429, 2013). "S100A8, S100A9, and S100A12 are produced by cells of myeloid origin and have been linked with cardiovascular disease (CVD)." (PMID 24453429, 2013). "Evidence supporting the important role of S100A9 in cardiovascular disease." (PMID 38504474, 2024). "Thus, S100A8 and S100A9 might serve as a useful biomarker and therapeutic target in human cardiovascular disease; besides, S100A8 and S100A9 blockers have been developed and are approved for clinical testing." (PMID 30886860, 2019). "Previous studies have shown that S100 protein family members are involved in cardiovascular disease, such as S100B, S100A8, S100A9, and S100A12." (PMID 31275446, 2019). "But the pathophysiological roles of S100A8, S100A9 and S100A8/A9 in cardiovascular diseases are incompletely explained." (PMID 24595267, 2014). "Despite functioning as a proinflammatory mediator, the pathophysiological roles of S100A8, S100A9, and S100A8/A9 complexes in cardiovascular disease are incompletely defined." (PMID 24595267, 2014).
inflammation (19 papers, 2012 to 2025). Aberrant reaction of the microcirculation characterized by movement of fluid and leukocytes from the blood into extravascular tissues. "S100A9 is a member of the S100 protein family, which binds calcium and plays a critical role in the recruitment and adhesion of immune cells such as neutrophils and monocytes, especially in inflammatory responses and inflammation-associated diseases." (PMID 40296873, 2025). "In a murine model of Klebsiella pneumoniae-induced pulmonary inflammation, global S100A9 deficiency resulted in diminished neutrophil recruitment into the lung alveoli and neutrophil accumulation in the intravascular space, indicating an impaired neutrophil migration." (PMID 36497202, 2022). "Caloprotectin, a heterodimeric complex of S100A8 and S100A9, is known as anti-microbial in human skin and highly expressed during chronic inflammation with compromised barrier function in skin." (PMID 27556734, 2016). "Consistent with previous mouse studies, genes associated with epidermal inflammation (e.g., IL-6, IL1B, S100A7, S100A8, and S100A9) and matrix metalloproteases (MMPs) were also significantly upregulated, as were E- and L-selectin, which are required for leukocyte entry into skin." (PMID 41150413, 2025). "Another study found that in mice exposed to mechanical ventilation/LPS injury, S100A8/A9 deficiency saved mice from lung inflammation, as seen by decreased alveolar-epithelial permeability, low neutrophil influx, and less cytokine/chemokine release in BAL of S100A9 KO mice compared to WT mice." (PMID 29180999, 2017). "This study investigated the mechanism by which S100A9 is involved in neutrophil activation, neutrophil extracellular trap (NET)-induced airway inflammation, and macrophage polarization in NA." (PMID 34285336, 2021). "It has been proposed that the transition from the chronic intestinal inflammation to CRC involves changes in ECM matrix proteins, such as FN, matrix regulators like serpin H1, and matrix enzymes and inflammatory factors, such as S100A8 and S100A9." (PMID 39195201, 2024). "S100A8, S100A9, and S100A12 were supposed to directly stimulate the production of mucin 5AC (MUC5AC), a major mucin protein in the airway which closely correlated with airway inflammation." (PMID 35348596, 2022). "In conclusion, the results of this study suggest that S100A9 may play a pivotal role in NA by enhancing neutrophil activation, NET formation, and macrophage polarization, and S100A9 is a therapeutic target of neutrophilic airway inflammation, especially in patients with SA." (PMID 34285336, 2021).
bacterial infection (17 papers, 2011 to 2026). "As a result, changes in the abundance of S100A9 may render patient populations more or less susceptible to bacterial infections." (PMID 34516771, 2021). "Two of these proteins, S100A9 and AZU1, are associated with neutrophils and play a key role in the host’s defense against bacterial infections." (PMID 38397935, 2024). "Bacterial infection has been shown to increase the abundance of S100A9 in the bovine uterine proteome." (PMID 36424602, 2022). "The biological function of METTL9 has yet to be revealed; however, our data point out a possible link between METTL9 activity and innate immune response to bacterial infection through histidine methylation of S100A9." (PMID 34562450, 2021). "Using site-specific antibodies, we evaluated whether His107 methylation of S100A9 was relatively static or dynamic during bacterial infection." (PMID 37522633, 2024). "Thus, understanding the contribution of METTL9-mediated histidine methylation of S100A9 in particular to immune response holds the potential of identifying new therapeutic targets and developing alternative treatment strategies for bacterial infections." (PMID 34562450, 2021). "Thus, METTL9-mediated S100A9 methylation appears to be involved in the innate immune response to bacterial infection." (PMID 34562450, 2021). "S100A9 is also an antimicrobial protein which is released by PMNs during bacterial infection." (PMID 32117815, 2020). "Critically, silencing of endogenous S100A9 expression in HBE cells significantly attenuated NF-κB activation and the overall cytokine response to bacterial infection, providing direct evidence for an epithelium-intrinsic autocrine amplification loop." (PMID 41853711, 2026). "In S100a9–/– mice, both WT and mutant strains showed enhanced infection compared to infections in C57BL/6 mice, reflecting the role of nutritional immunity in defending against bacterial infection." (PMID 40996229, 2025). "Importantly, the difference in bacterial infection between the WT and mutant strains observed in C57BL/6 mice was dwarfed in S100a9–/– mice, underscoring the role of ExsIms in overcoming CP-mediated iron sequestration." (PMID 40996229, 2025). "However, serum S100A9 levels in patients combined with bacterial infections were not statistically different from those in patients without combined bacterial infections." (PMID 40478888, 2025). "In addition to its regulatory role in the expression of S100A9 and lipocalin-2 as we reported here, whether IL22 also contributes to urothelium defense mechanisms against bacterial infection by regulating HUC production of HA or HUC expression of TLR4/CD14 remains to be elucidated." (PMID 25354343, 2014).
neurodegenerative disease (14 papers, 2014 to 2025). A disorder of the central nervous system characterized by gradual and progressive loss of neural tissue and neurologic function. "Elevated levels of S100A9 have been associated with neuroinflammation, and this increase has been implicated in the pathogenesis of neurodegenerative diseases." (PMID 39767615, 2024). "The proinflammatory protein S100A9, a key component of the alarmin family, has emerged as a critical mediator of microglial activation in neuroinflammatory and neurodegenerative diseases." (PMID 41204337, 2025). "The calcium-binding protein S100A9 is recognized as an important component of the brain neuroinflammatory response to the onset and development of neurodegenerative disease." (PMID 37686007, 2023). "S100A9 is a member of a family of structurally homologous calcium-binding S100 proteins, which are involved in many inflammatory and neurodegenerative diseases." (PMID 35912090, 2022). "Pro-inflammatoryand amyloidogenic S100A9 protein is central tothe amyloid-neuroinflammatory cascade in neurodegenerative diseases.Polyoxometalates (POMs) constitute a diverse group of nanomaterials,which showed potency in amyloid inhibition." (PMID 34080430, 2021). "The inhibition and complete hindering of S100A9 amyloidpathways may be used in the therapeutic applications targeting theamyloid-neuroinflammatory cascade in neurodegenerative diseases." (PMID 34080430, 2021). "Novel therapies that prevent deamidation of brain proteins such as S100A9 could therefore represent an effective approach to the treatment of human neurodegenerative diseases." (PMID 26892330, 2016). "We have also recently reported that S100A9 can undergo LLPS and even form heterotypic droplets with another neurodegenerative disease-related protein—alpha-synuclein." (PMID 41009529, 2025). "We provided a detailed characterisation of our cohort, including an analysis of biomarkers such as NfL, S100A9, kynurenic acid (KYNA), and GAD1, all of which are well documented in the literature for their importance in neurodegenerative diseases." (PMID 39767615, 2024).
infectious disease (7 papers, 2014 to 2024). A disorder directly resulting from the presence and activity of a microbial, viral, or parasitic agent in humans. "At present, S100A8, S100A9, and S100A12 proteins generated from human or mouse sources have been extensively studied and proven to be powerful in the prevention and treatment of infectious diseases." (PMID 38256103, 2024). "S100A8, S100A9, and S100A12 proteins are important members of the S100 protein family, act primarily as congenital immunomodulators, and are closely related to the occurrence of infectious diseases." (PMID 38256103, 2024).
metabolic disease (6 papers, 2015 to 2023). A congenital disorder (due to inherited enzyme abnormality) or acquired (due to failure of a metabolically important organ) disorder resulting from an abnormal metabolic process. "S100A8 and S100A9 were identified as the potentially perturbed proteins, which were related to immunological disease and metabolic disease." (PMID 35540476, 2018). "Biochemical indexes of metabolic disorders, such as FBG, HOMA-IR, TG, and TC are weakly associated with serum S100A9 levels." (PMID 25993652, 2015). "FBG, HOMA-IR, TG, and TC, indicators of metabolic disorders, showed a weak correlation with serum S100A9 (r = -0.41, -0.40, 0.47, and 0.49, respectively, P < 0.05)." (PMID 25993652, 2015). "Data from this analysis show that S100A9 is more sensitive in NASH than in T2DM, which strongly suggests that S100A9 may be an ideal biomarker for hepatic progression in NAFLD but not for metabolic disorders." (PMID 25993652, 2015).
immune disease (4 papers, 2014 to 2025). "In immune disease or inflammatory conditions, the S100A9 level increases sharply, enhancing integrin expression and recruiting monocytes to the inflammatory position." (PMID 39877635, 2025).
kidney disease (4 papers, 2021 to 2026). "Among the remaining proteins, S100a9 and Spp1 have clear functions in kidney disease." (PMID 39911133, 2025). "Cohorts of male and female S100a9+/+, S100a9+/-, and S100a9-/- NZBWF1 mice were followed for up to 8 months of age or until severe renal disease was present (n = 5-11)." (PMID 34220829, 2021). "Taken together, S100a9 exerts an immunosuppressive function in male NZBWF1 mice effectively moderating lupus-like disease development via inhibition of type I interferon production, lymphocyte activation, autoantibody production and the development of renal disease." (PMID 34220829, 2021). "Furthermore, male, but not female, S100a9-/- NZBWF1 mice showed increased disease development including elevated splenomegaly, hyperactive B and T cells, and accelerated renal disease." (PMID 34220829, 2021).
Hematologic Malignancies (3 papers, 2020 to 2023). "Accumulating evidence showed that S100A8 and S100A9 play pathogenic and prognostic roles in solid cancer types and hematological malignancies." (PMID 37691822, 2023).
lung (3 papers, 2021 to 2025). "Inhibition of S100A8 and S100A9 by neutralizing antibodies also attenuated lung neutrophilia in a model of serotype 3 IPD, surprisingly without affecting bacterial clearance or survival of mice." (PMID 37467233, 2023).
neoplastic disorders (3 papers, 2006 to 2019). "Dysregulated expression of S100 proteins, including S100A9, has been reported in the epidermis as a response to stress and in association with neoplastic disorders." (PMID 17187679, 2006). "Recent studies have shown that S100A8/S100A9 is associated with various neoplastic disorders." (PMID 31208368, 2019).
respiratory diseases (3 papers, 2014 to 2021). "The clinical significance of our result is borne out by the possibility of passive immunization with anti-S100A9 antibody to reduce the severity of respiratory disease associated with IAV infection." (PMID 24391503, 2014). "The analysis yielded seven SARS-CoV-2 specific genes including CSF2 [GM-CSF] (colony-stimulating factor 2) and calcium-binding proteins (such as S100A8 and S100A9), which are known to be involved in respiratory diseases." (PMID 34376762, 2021). "And compared with S100A8 and S100A9, SA100A12 is more considered as a marker for respiratory diseases with neutrophilic inflammation." (PMID 34457122, 2021).
benign tumors (1 paper, 2022). "An elevated level of S100A9 was detected in inflammation, benign tumors, and various malignancies." (PMID 36072966, 2022).
colon (1 paper, 2012). "Indeed in vivo studies with S100a9-/- animals highlighted a crucial role for S100a8/a9 in the promotion of inflammation and inflammation-induced carcinogenesis in models of antigen-induced arthritis and colon carcinogenesis, respectively." (PMID 23241281, 2012).
S100A9 also shares sentences with these, for which no sentence is quoted: acute myocardial infarction (7 papers); benign prostatic hyperplasia (5); coronary artery disease (5); adenocarcinoma (3); chronic kidney disease (3); colon polyps (3); gastric adenocarcinoma (3); gingivitis (3); head and neck cancer (3); liver inflammation (3); pancreatitis (3); acute appendicitis (2); acute respiratory distress syndrome (2); Barrett esophagus (2); bone marrow fibrosis (2); cholangiocarcinoma (2); chronic lymphoid leukemia (2); chronic pancreatitis (2); clear cell renal cell carcinoma (2); diabetic retinopathy (2); dysplasia (2); E. coli infection (2); encephalitis (2); epidermal disease (2); hemorrhage (2); intracranial aneurysms (2); keloid (2); liver abscesses (2); Lung Injury (2); malaria (2).
A further 133 diseases each share a sentence with S100A9 in 2 papers or fewer.